Y_RNA (Y RNA )
Gene: Miscellaneous RNA gene on chromosome 20 (450,663 to 450,762, forward strand). Ensembl gene ENSG00000206797.
Homologues: Orthologues: chimpanzee Y_RNA (98% identical), macaque Y_RNA (88% identical). Paralogues in human: Y_RNA (83% identical), RNY3 (82% identical), Y_RNA (82% identical), Y_RNA (81% identical), Y_RNA (80% identical), RNY3P1 (79% identical), Y_RNA (79% identical), RNY3P14 (78% identical), RNY3P4 (78% identical), RNY3P9 (78% identical), Y_RNA (78% identical), RNY3P16 (77% identical), and 88 more.